PTGS1 (prostaglandin-endoperoxide synthase 1)
Diseases named in the same sentence as PTGS1 in open-access papers (continued):
Sharing a sentence is not in itself a finding about the gene and the disease.
Arthritis (5 papers, 2019 to 2024). Inflammation of a joint. "Another study confirmed wide genomic regions that caused inflammatory arthritis in a heterogeneous mice cohort and identified PTGS1 as a key candidate based on the differential expression in arthritis." (PMID 33800915, 2021). "A low level of SPDEF leads to an increase in the expression of ZBTB46, thus facilitating an abundance of prostaglandin endoperoxide synthase 1 (PTGS1), which was reported to participate in inflammation, arthritis, and cancer pathophysiology." (PMID 31181727, 2019). "Besides, PTGS1 has been connected with multiple pathological disorders including inflammation, arthritis, and cancer." (PMID 33800915, 2021). "Previous studies have demonstrated that PTGS1 and PTGS2 are both highly expressed in the joints of patients with OA, which could provide drug targets for treating arthritis." (PMID 35992559, 2022). "Therefore, ADRB2, AHR, CRP, IRF1, PTGS1, SPP1 and other targets can be used as potential targets for CC in the treatment of arthritis, and it is of great significance to explore its role of CC in the treatment of arthritis." (PMID 37637408, 2023).
lung carcinoma (5 papers, 2013 to 2025). "A total of 83 potential targets of ROB in lung cancer were collected and further screened by using Cytoscape software, and 7 targets of PTGS2, CYP19A1, PTGS1, AR, CYP17A1, PTGES and SRD5A1 were obtained as hub genes and 7 hub targets had good binding energy with ROB." (PMID 39450260, 2024). "The hub targets of ROB action in lung cancer were further analyzed by combining 14 targets from Degree≥6, 10 targets each from MCC and MNC algorithms, and finally 7 common targets such as PTGS2, CYP19A1, PTGS1, AR, CYP17A1, PTGES and SRD5A1 were obtained from the final screening." (PMID 39450260, 2024).
prostate carcinoma (5 papers, 2008 to 2025). A carcinoma that arises from epithelial cells of the prostate gland. "This study investigated the potential association between the single nucleotide polymorphism (SNP) -842A>G (rs10306114) of the PTGS1 gene and SNP-765G>C (rs20417) of the PTGS2 gene with prostate cancer (PCa) and benign prostate hyperplasia (BPH)." (PMID 40184332, 2025).
depression (4 papers, 2019 to 2022). "The underlying mechanism of PTGS1, the miR-15b/miR-92b common targeting protein, involved in the pathogenesis of depression, is still ambiguous." (PMID 34829725, 2021). "Three candidate genes implicated in anxiety and depression were selected: Htr2b29 (encoding the Serotonin receptor 2b), Cacna1c30 (encoding the α1C subunit of the voltage-gated L-type calcium channel Cav1.2) and Ptgs1 (encoding a prostaglandin-synthesising enzyme Cyclooxygenase-1)." (PMID 31253786, 2019). "Clinical data showed that both miR-15b-5p and miR-92b-3p were down-regulated in OSA patients, while their common target gene, PTGS1, was up-regulated, particularly in those with depression." (PMID 34829725, 2021). "Next, we validated that miR-15b-5p/miR-92b-3p and their target mRNA, PTGS1, were substantially decreased and increased, respectively, in OSA both in vivo and in vitro, while PTGS1 were further increased in OSA patients with depression and in response to IHR stimuli." (PMID 34829725, 2021). "Thus, miR-92b-3p might play anti-inflammatory, antioxidant, and MAOA-inhibiting roles in the progression of OSA and the development of depression by regulating PTGS1 via NF-κB1/SP1 signaling." (PMID 34829725, 2021). "Increased enzyme activity of PTGS1 and PTGS2 has been implicated as another mechanism in depression, and herb drugs reducing arachidonic acid levels through inhibiting PTGS1/2 could be used to treat depression in the chronic unpredictable mild stress rat model." (PMID 34829725, 2021). "Hence, targeting the MAOA-related PTGS1 signaling pathway by miR-15b-5p/miR-92b-3p could provide a novel therapeutic avenue for treating OSA-related depression." (PMID 34829725, 2021). "Notwithstanding that limitation, this study does correlate miR-15b/miR-92b under-expression and PTGS1 over-expression with MAOA hyperactivity, oxidative stress, and augmented apoptosis of neuron cells in OSA-related depression." (PMID 34829725, 2021). "For the first time, we found that miR-15b-5p/miR-92b-3p mimics could inhibit MAOA activity through directly targeting PTGS1 via NF-κB1/SP1 signaling and may be developed as new drug targets for depression treatment in OSA patients." (PMID 34829725, 2021). "PTGS1 gene expression (24.2 ± 41.3 versus 3.3 ± 3.2-fold change, adjusted p = 0.002) was increased in all sleep-disordered breathing patients with depression versus those without depression." (PMID 34829725, 2021).
ischemic stroke (4 papers, 2021 to 2025). A stroke disorder caused by obstruction of blood flow to the brain, due to thrombotic (local blood clot formation) or embolic (due to a blood clot or other material traveling from another site) event. "Follow-up studies further identified a significant association between the PTGS1 locus and ischemic stroke (IS) recurrence in Chinese patients." (PMID 41465406, 2025). "For example, 31348992 Intersection analysis between DZXXI's putative targets with ischemic stroke-associated genes identified two important targets (PTGS1, PTGS2)." (PMID 34325669, 2021). "Thus, PTGS1 rs1330344 might be considered as the strongest predictor of laboratory AR among the analyzed SNPs, both in the whole cohort of ischemic stroke and noncardioembolic patients." (PMID 36289824, 2022).
leukemia (4 papers, 2017 to 2025). A malignant (clonal) hematologic disorder, involving hematopoietic stem cells and characterized by the presence of primitive or atypical myeloid or lymphoid cells in the bone marrow and the blood. "There was a significant change in the expression of PTGS1 in diverse tumors such as the brain, kidney, nasopharyngeal, colon, leukemia, and other hematopoietic reticuloendothelial systems and various related pathophysiological conditions." (PMID 29247872, 2017). "Since the importance of PGE2-mediated induction of β-catenin for the formation and maintenance of LSC was initially discovered through upregulation of Ptger and Ptgs1 in murine leukemia, we subsequently focused on the investigation of Pla2g4a as a leukemia essential gene." (PMID 34502319, 2021). "There are several reports on the in vitro effects of NSAIDs and the expression of PTGS1 and PTGS2 in leukaemia cell lines." (PMID 40444088, 2025).
osteoarthritis (4 papers, 2022 to 2026). A noninflammatory degenerative joint disease occurring chiefly in older persons, characterized by degeneration of the articular cartilage, hypertrophy of bone at the margins and changes in the synovial membrane. "We also find a decrease in PTGS1 in degraded compared with in intact osteoarthritis-affected chondrocytes." (PMID 40205036, 2025). "Furthermore, a decrease in COX1(cytochrome C oxidase 1, synonym: cyclooxygenase-1) (synonym: PTGS1, prostaglandin-endoperoxide synthase 1) expression in degraded compared with intact osteoarthritis-affected chondrocytes was reported." (PMID 40630467, 2025). "A previous study has reported that neither COX-2 inhibitors nor the genetic deficiency of Ptgs1−/− mice or Ptgs2−/− mice exhibit a chondroprotective effect in surgery-induced osteoarthritis mice." (PMID 36078169, 2022).
Peptic ulcer (4 papers, 2013 to 2025). The term peptic ulcer refers to acid peptic injury of the digestive tract, resulting in mucosal break reaching the submucosa. "In our analyses, both PTGS1 and PTGS2 proteins are linked to Peptic ulcer and Peptic ulcer haemorrhage ADRs with significant q-values." (PMID 34679164, 2021).
coagulopathy (3 papers, 2020 to 2025). "Analysis of the targets overlapped such as PTGS1, PTGS2, PIK3CG, and PECAM1 in the pathological processes of hemorheological abnormality and coagulopathy implied that inflammation and immunity were also important for QS-BSS which need further study." (PMID 32190085, 2020).
COVID-19 (3 papers, 2020 to 2021). A disease caused by infection with severe acute respiratory syndrome coronavirus 2. "Its key compounds including quercetin, kaempferol, 7-O-methylisomucronulatol, baicalein, and formononetin target IL6, MAPK8, PTGS2, PTGS1, and NCOA2 to regulate multiple signal pathways of TCM and play a therapeutic role in the recovery period of COVID-19." (PMID 34335247, 2021).
gastric ulcer (3 papers, 2013 to 2024). An ulcerated lesion in the mucosal surface of the stomach. "The pharmacology network explained target genes related to the identified metabolites to possess 672 interactions between the 18 identified metabolites and 379 genes, among which PTGS2, MMP2 and PTGS1 were the top annotated genes related to gastric ulcer." (PMID 38355510, 2024). "The PTGS2, MMP2 and PTGS1 were the top annotated genes related to gastric ulcer." (PMID 38355510, 2024).
liver fibrosis (3 papers, 2020 to 2023). "Study has shown that hypermethylation of cyclic prostaglandin synthase 1 (PTGS1) genes represses their transcription and ultimately upregulates the expression of α-SMA and COL1A1 genes, promoting HSC activation and liver fibrosis." (PMID 36059967, 2022).
myocardial infarction (3 papers, 2015 to 2023). Gross necrosis of the myocardium, as a result of interruption of the blood supply to the area, as in coronary thrombosis. "We also found and replicated biallelic combinations of TGFB1 with FGB, TGFB1 with CRP and IFNG with PTGS1 genetic variants associated with myocardial infarction providing a detectable cumulative effect." (PMID 26658659, 2015).
acute gastritis (2 papers, 2022 to 2025). "In the mouse model, oral administration of ICAC significantly alleviated acute gastritis by preserving mucosal integrity, preventing prostaglandin E2 depletion, and enhancing Ptgs1 and Muc6 expression in mice, while suppressing inflammatory mediator production in gastric tissues." (PMID 41423315, 2025). "In addition, PTGS2, TRL4, MMP9, JAK1, EGFR, CYP2C19, and PTGS1 were identified as crucial anti-gastritis target genes in C. cassia." (PMID 35336597, 2022).
Alzheimer disease (2 papers, 2024 to 2025). A progressive, neurodegenerative disease characterized by loss of function and death of nerve cells in several areas of the brain leading to loss of cognitive function such as memory and language. "The expression of PTGS1 and PTGS2 changes throughout the progression of Alzheimer’s disease pathology and is believed to contribute to the neuroinflammatory aspect of the disease." (PMID 38977662, 2024). "Diving deeper into to the evidence chains, Sulindac, an inhibitor of PTGS1 and PTGS2, has been predicted as a potential therapy for FXS by linking these two proteins to their involvement in Alzheimer’s disease and amyloid precursor protein (APP) processing." (PMID 38977662, 2024).
bladder cancer (2 papers, 2024 to 2025). "Along this line, patients with bladder cancer treated with aspirin, an inhibitor of cyclooxygenase (COX) 1 and 2 (encoded by PTGS1 and PTGS2, respectively), while undergoing intravesical immunotherapy benefited from better response rates." (PMID 39114912, 2024).
cervical cancer (2 papers, 2012 to 2016). A primary or metastatic malignant neoplasm involving the cervix. "Our laboratory and others have demonstrated elevated expression of PTGS1, PTGS2, the E-series prostanoid receptors PTGER2 and PTGER4 together with enhanced biosynthesis and signaling of PGE2 in cervical carcinomas." (PMID 22442729, 2012). "We have previously shown that PTGS1, PTGS2, PTGER2 and PTGER4 are elevated in cervical cancers." (PMID 22442729, 2012).
colitis (2 papers, 2012 to 2020). Inflammation of the colon. "mRNA levels of Ptgs1, Ptgs2, Abcc4, and Hpgd were significantly decreased in LP macrophages from Slco2a1−/− mice with DSS-induced colitis when compared with their WT counterparts." (PMID 32184453, 2020).
hepatocellular carcinoma (2 papers, 2016 to 2023). A malignant tumor that arises from hepatocytes. "Finally, sinapine thiocyanate from SS significantly decreases the protein expression of PTGS1, PTGS2, Bcl-2, MMP-2 and MMP-9 and increases the protein expression of Bax to prohibit the proliferation, migration and invasion of hepatocellular carcinoma cells in SMMC-7721." (PMID 37124205, 2023).
influenza (2 papers, 2020 to 2022). An acute viral infection of the respiratory tract, occurring in isolated cases, in epidemics, or in pandemics; it is caused by serologically different strains of viruses (influenzaviruses) designated A, B, and C, has a 3-day incubation period, and usually lasts for 3 to 10 days. "A holistic C-D-T network was generated by merging three networks to determine the factors involved in influenza-associated inflammation, which yielded two main active compounds (BS and PG) and main targets (PTGS1 and PTGS2)." (PMID 32854331, 2020). "Of them, many had relevance in influenza infection such as genes responsible for virus entry (Anxa1/2, Cd14), interferon signaling (Dusp10, Tnfsf13), or prostaglandin synthesis (Ptgs1/2)." (PMID 35629310, 2022).
lung fibrosis (2 papers, 2018 to 2025). "Prostaglandin G/H synthase 1 (PTGS1), arachidonate 5-lipoxygenase, and several other targets are associated with arachidonic acid metabolism, which is probably associated with progression of inflammation related to pulmonary fibrosis." (PMID 30092799, 2018). "The actions of PTGS1 and PTGS2 are interconnected, collectively impacting the advancement of lung fibrosis." (PMID 40003932, 2025).
lymphoma (2 papers, 2023 to 2024). A malignant (clonal) proliferation of B- lymphocytes or T- lymphocytes which involves the lymph nodes, bone marrow and/or extranodal sites. "Consistent with the increased levels of the cyclooxygenase pathway metabolites, we found that Ptgs2 but not Ptgs1 gene expression was dramatically induced up to 250-fold in Alox8-deficient lymphoma cells, compared to that in control shRen lymphoma cells." (PMID 36750552, 2023).
mastitis (2 papers, 2009 to 2022). Inflammation of breast tissue during lactation or postpartum due to an obstructed duct or infection.
osteoporosis (2 papers, 2021 to 2023). A condition of reduced bone mass, with decreased cortical thickness and a decrease in the number and size of the trabeculae of cancellous bone (but normal chemical composition), resulting in increased fracture incidence. "The MYLK rs12163585 minor allele was associated with a decreased risk of osteoporosis and benign breast tumors in Asia, while the PTGS1 rs1213265 minor allele detected mostly in Africa was associated with an increase in both diseases." (PMID 33800915, 2021). "There were 60 single nucleotide polymorphisms (SNPs) and 12 SNPs in the MYLK and PTGS1 genes, associated with benign breast tumors and osteoporosis." (PMID 33800915, 2021). "Our data demonstrated the association of the MYLK gene and PTGS1 gene variants with osteoporosis and benign breast tumor risk and the impact of ovariectomy on osteoporosis in Korean women." (PMID 33800915, 2021). "In this prospective GWAS, we identified an association between MYLK rs12163585 and PTGS1 rs1213265 variants, ovariectomy, and the risk of osteoporosis using HEXA Korean women data." (PMID 33800915, 2021). "In addition, rs1213265 in PTGS1 showed significant associations with benign breast tumors (OR = 1.81, 95% CI: 1.29–2.53, p = 6.03 × 10−4) and osteoporosis (OR = 2.03, 95% CI: 1.36–3.03, p = 4.90 × 10−4)." (PMID 33800915, 2021). "Genetic variants in MYLK and PTGS1 are associated with both benign breast tumors and osteoporosis." (PMID 33800915, 2021). "Analysis of the differences in the risk of osteoporosis and ovariectomy in the MYLK rs12163585 and PTGS1 rs1213265 genotypes showed significant associations with each genotype." (PMID 33800915, 2021). "We analyzed the association between benign breast tumors and osteoporosis and MYLK and PTGS1 SNPs." (PMID 33800915, 2021). "In this study, after excluding genes unrelated to osteoporosis or breast disease, we focused on the MYLK and PTGS1 genes, which presented the least p-value and the highest odds ratio for both diseases." (PMID 33800915, 2021). "Based on network pharmacology, core targets (PTGS1 and PTGS2) and key ingredients (kaempferol, beta-sitosterol, stigmasterol, fumarine and frutinone A) that might play pivotal roles in treating osteoporosis were screened out." (PMID 37464262, 2023). "Therefore, PTGS1 and PTGS2 might be involved in the development and treatment of osteoporosis, and our results of network pharmacology were in line with previous studies." (PMID 37464262, 2023).
pancreatic cancer (2 papers, 2013 to 2022). "PTGS1 is involved in prostaglandin synthesis and it is deregulated in pancreatic cancer." (PMID 24204564, 2013).
schizophrenia (2 papers, 2006 to 2023). A major psychotic disorder characterized by abnormalities in the perception or expression of reality. "Malfunctions of PTGH impact the proper action of PTGS1 and fraught with the angiopathy, and the risk of thrombosis largely frequent among patients with schizophrenia." (PMID 36747015, 2023). "Hence, the selected elements of hsa0059, hsa04611, and hsa04923 pathways and direct relation of PTGS1 to serotonergic synapse plasticity might be considered as ancient factors of schizophrenia etiology." (PMID 36747015, 2023).
ankylosing spondylitis (1 paper, 2019). An autoimmune chronic inflammatory disorder characterized by inflammation in the vertebral joints of the spine and sacroiliac joints. "PTGS1 was recently proposed as a candidate gene for ankylosing spondylitis, a disease accompanied by bone overgrowth." (PMID 31316547, 2019).
bacterial pneumonia (1 paper, 2023). Acute infection of the lung parenchyma caused by bacteria (e.g., Streptococcus pneumoniae, Haemophilus influenzae, Chlamydia pneumoniae, Mycoplasma pneumoniae, and Legionella pneumophila). "In cases of bacterial pneumonia, the mRNA expression of MAPK1 and CYP3A4 increased significantly, while those of PTGS1 and PTGS2 decreased synonym." (PMID 37741847, 2023).
Cerebral ischemia (1 paper, 2021). Restriction of arterial blood supply to the brain associated with insufficient oxygenation to support the metabolic requirements of the tissue. "Among them, the most interacting genes such as PTGS1 and PPARG are important related genes in the ROS/RNS pathway of E. breviscapus treatment of cerebral ischemia." (PMID 34531475, 2021).
cerebrovascular disease (1 paper, 2021). "The genetic variation in PTGS1 may increase the risk for cerebrovascular disease events." (PMID 34194527, 2021).
cervical adenocarcinoma (1 paper, 2012). An adenocarcinoma arising from the cervical epithelium. "Using HeLa cervical adenocarcinoma cells, we found that seminal plasma (SP) induced the expression of the inflammatory enzymes, prostaglandin endoperoxide synthase (PTGS1 and PTGS2), cytokines IL-6, IL-11 and the angiogenic factor VEGF-A in vitro." (PMID 22442729, 2012). "Using HeLa cervical adenocarcinoma cells, we found that seminal plasma (SP) induced the expression of the inflammatory enzymes, prostaglandin endoperoxide synthase (PTGS1 and PTGS2), cytokines interleukin (IL) -6, and -11 and vascular endothelial growth factor-A(VEGF-A)." (PMID 22442729, 2012). "HeLa cervical adenocarcinoma cells were treated with 1∶100 dilution of SP or vehicle (PBS) for 6 hours and the mRNA expression of PTGS1 and PTGS2 was determined by quantitative RT-PCR analysis." (PMID 22442729, 2012).
cholestasis (1 paper, 2022). Impairment of the bile flow caused by obstruction within the liver, or outside the liver in the bile duct system. "Moreover, Q7R can also reduce TNF-α, IL-1β, PTGS1, PTGS2, NCOA2, and NF-κB levels and alleviate the inflammatory response caused by cholestasis." (PMID 36699093, 2022).